RBM24 (RNA binding motif protein 24)
Diseases named in the same sentence as RBM24 in open-access papers (continued):
Sharing a sentence is not in itself a finding about the gene and the disease.
cancer (13 papers, 2016 to 2025). A tumor composed of atypical neoplastic, often pleomorphic cells that invade other tissues. "It appears that post-translational modifications of RBM24 play an important role in regulating its activity, but the mechanisms underlying this regulation remain largely elusive across different cancers with dysregulated RBM24 expression." (PMID 35406615, 2022). "Future studies will be necessary to provide further insights into the mechanisms underlying RBM24 dysregulation during malignant transformation and determine its activity in specific cancer cells." (PMID 35406615, 2022). "Furthermore, Rbm24 has been implicated in directly regulating cell proliferation and tumor growth in several cancers 30-33." (PMID 39113792, 2024). "Although Rbm24 has been extensively studied in the field of heart development, skeletal muscle regeneration and cancer 23-29, its roles in the central nervous system remain largely unexplored." (PMID 39113792, 2024). "At present, only limited studies have been conducted to clarify the implication of RBM24 in a few cancer types." (PMID 35406615, 2022). "Inappropriate epigenetic modifications can also contribute to dysregulation of RBM24 expression in cancers." (PMID 35406615, 2022). "Bioinformatic analyses provide correlative evidence for a possible involvement of RBM24 in the development of several cancers." (PMID 35406615, 2022). "RBM24 is an evolutionarily conserved RBP that regulates several post-transcriptional events in cancer cells." (PMID 35406615, 2022). "This review discusses recent advances in studying the roles of RBM24 in cancer progression and proposes future directions in the research of RBM24-mediated post-transcriptional regulation of tumorigenesis." (PMID 35406615, 2022). "Recently, there is increasing evidence showing that RBM24 expression is frequently dysregulated in human cancers." (PMID 35406615, 2022). "This review discusses recent findings on the potential function of RBM24 in tumorigenesis and provides future directions for better understanding its regulatory role in cancer cells." (PMID 35406615, 2022). "As a carcinoma inhibitor gene, RBM24 regulates Twist1 to achieve LN metastasis and EMT suppression in HSCC." (PMID 36213838, 2022). "Ping-Ying Guo at Hebei Medical University in Shijiazhuang, China, and co-workers investigated the role of RBM24, known to be involved in other cancers, and found increased levels in BC tissues." (PMID 34021255, 2021). "RNA‐binding motif protein 24 (RBM24) functions as a splicing regulator, which is critical for organ development and is dysregulated in human cancers." (PMID 34709758, 2021). "It is also important to understand how the expression and activity of Rbm24 or Rbm38 are dysregulated in cancer cells." (PMID 32806768, 2020). "Previous studies have reported that RBM24 is involved in the regulation of p63 and p21 mRNA stability by binding to the AU-rich elements (AREs) in their 3'UTRs in different human cancer cell lines." (PMID 33224130, 2020). "A further understanding of the functional consequences of Rbm24 and Rbm38 in regulating cancer-related gene expression should help to define novel therapeutic strategies for modulation of their activity." (PMID 32806768, 2020). "In addition to mRNA targets, RBM24 also directly or indirectly regulates the expression of non-coding RNAs (ncRNAs) in cancer cells." (PMID 35406615, 2022). "Third, the activity of RBM24 in tumorigenesis may be also dependent on the expression of other cancer-related genes (genetic background)." (PMID 35406615, 2022). "Indeed, we found that RBM24 protect cancer cells from ferroptosis by stabilizing mRNA of SLC7A11, an inhibitor of ferroptosis." (PMID 36478739, 2022). "These works identify a critical role of the eIF4E-binding motif to modulate RBM24/RBM38 activity in cancer cells and raise the possibility that disrupting RBM24/RBM38-eIF4E complex may represent a potential therapeutic approach for cancer treatment." (PMID 35406615, 2022).
cancer (continued). "This raises a possibility that the decrease or increase in RBM24 expression during cancer progression may be dependent on its epigenetic modifications." (PMID 35406615, 2022). "Thus, deciphering the mechanism of RBM24-mediated protein–protein interaction in the post-transcriptional regulation of gene expression should help to define therapeutic strategies for cancer treatment." (PMID 35406615, 2022). "Therefore, it will be interesting to determine the phosphorylation status of RBM24 and identify possible kinases that are potentially involved in its post-translational modifications in different cancer tissues." (PMID 35406615, 2022). "In this regard, when considering dysregulation of RBM24 expression in cancer tissues, it may also need to be taken into consideration its phosphorylation status in addition to the analysis of its mRNA or protein levels." (PMID 35406615, 2022). "Importantly, data from the Human Protein Atlas indicate that RBM24 displays heterogeneous subcellular distribution in specific cancer tissues with a population of cells showing nuclear localization." (PMID 35406615, 2022). "Thus, systematic profiling of RBM24-regulated events in various cancers will be of interest to understand its implication in the pathological processes." (PMID 35406615, 2022). "There is also evidence that the function of RBM24 in cancers may be subjected to post-transcriptional regulation." (PMID 35406615, 2022). "Whether and how RBM24 regulates these aspects of the post-transcriptional process in cancer cells remains largely elusive." (PMID 35406615, 2022). "Compared to embryonic development, only a few RBM24 targets have been identified in cancers." (PMID 35406615, 2022). "The antitumor role of RBM24 in a few carcinomas is noteworthy." (PMID 36213838, 2022). "What’s more, several studies demonstrated that RBM24 might regulate the stability of mRNA transcripts in different human cancer cell lines." (PMID 34053447, 2021). "Therefore, our results indicated that the downregulation of RBM24 in female LIHC patients could cause the loss of normal function of TXN and inhibit cancer progression." (PMID 39175079, 2024). "Second, RBM24 might regulate unique target genes in different kinds of cancers." (PMID 35406615, 2022). "Thus, further characterization of RBM24 expression and function across different cancers using clinical samples and appropriate animal models will be necessary to determine the mechanisms by which RBM24 modulates cancer development." (PMID 35406615, 2022). "Importantly, targeting RBM24-mediated protein–protein interactions may also represent a potential therapeutic approach for cancer treatment." (PMID 35406615, 2022). "Thus, it would be interesting to determine the role of RBM24 in these tumors, which may lay a foundation for the development of novel cancer therapeutics." (PMID 36478739, 2022). "However, the priming substrate of Stk38 in RBM24 remains to be determined and whether this phosphorylation also occurs in cancer cells merits further investigation." (PMID 35406615, 2022). "However, recent studies have demonstrated that RBM24 also regulates cancer progression." (PMID 34021255, 2021). "Thus, it could be speculated that RBM24 might have an effect on promoting cancer." (PMID 34053447, 2021).
cancer (continued). "A related aspect is the lack of systematic examination of RBM24 subcellular localization in cancer cells." (PMID 35406615, 2022). "However, at least in several cancer cell lines, phosphorylation of the serine residue by glycogen synthase kinase 3 (GSK3) prevents the interaction with eIF4E and converts Rbm24 or Rbm38 into an activator of mRNA translation." (PMID 32806768, 2020). "Since Rbm24 protein contains a canonical RRM that binds to the GU-rich ligand present in a wide spectrum of target mRNAs, it would be not surprising that inappropriate regulation of its expression or function in humans perturbs the homeostasis of protein synthesis and leads to cancer development." (PMID 32806768, 2020).
heart diseases (3 papers, 2017 to 2024). "To understand the functional involvement of RBM24 in postnatal heart and potential contribution to heart diseases, we generated a conditional deletion allele of the mouse Rbm24 gene by homologous recombination in mouse ESCs." (PMID 30267374, 2019). "Importantly, the global AS analysis revealed that RBM24 regulated a network of genes previously reported to associate with heart diseases." (PMID 30267374, 2019). "Considering the importance of the phosphorylation state of protein in identifying the pathophysiological basis of sarcomeric dysfunctions, regulating the phosphorylation of Rbm24 could be a potential therapeutic strategy in heart diseases." (PMID 28322254, 2017). "However, the role of RBM24 in postnatal heart development and heart disease has not been investigated." (PMID 30267374, 2019).
infection (3 papers, 2018 to 2022). The state of being infected such as from the introduction of a foreign agent such as serum, vaccine, antigenic substance or organism. "This study generated FaDu-OE-RBM24 cells by infection with lentiviral particles and evaluated the RBM24 overexpression efficiency using qRT-PCR and WB analyses." (PMID 36213838, 2022). "An enhanced translation and delayed RNA synthesis during the early phase of infection was observed in RBM24 silencing cells." (PMID 29380205, 2018).
myopathy (1 paper, 2020). A disease of the muscle in which the muscle fibers do not function properly. "Equally as important, Rbm24 also regulates AS of genes that are relevant to myopathy." (PMID 33042276, 2020). "However, we did find studies showing several Rbm24-regulated AS events, which were demonstrated to be involved in different biological processes, such as muscle hypertrophy, myogenesis, muscle regeneration and myopathy." (PMID 33042276, 2020).
neurological disorders (1 paper, 2024). "The study concludes that targeting the Rbm24/Notch1 signaling axis could be a promising strategy for the treatment of early-stage PD and related neurological disorders." (PMID 39113792, 2024).
RBM24 also shares sentences with these, for which no sentence is quoted: Myotonic Dystrophies (2 papers); Anophthalmia (1); cataract (1); deafness (1); endometrial adenocarcinoma (1); familial dilated cardiomyopathy (1); hypopharyngeal cancer (1); Hypopharyngeal Squamous Cell Carcinoma (1); left ventricular noncompaction (1); melanoma (1); myotonic dystrophy type 2 (1); rectum adenocarcinoma (1); testis cancer (1).